TAB2 (TGF-beta activated kinase 1 (MAP3K7) binding protein 2)
Description:
Adapter required to activate the JNK and NF-kappa-B signaling pathways through the specific recognition of 'Lys-63'-linked polyubiquitin chains by its RanBP2-type zinc finger (NZF). Acts as an adapter linking MAP3K7/TAK1 and TRAF6 to 'Lys-63'-linked polyubiquitin chains. The RanBP2-type zinc finger (NZF) specifically recognizes Lys-63'-linked polyubiquitin chains unanchored or anchored to the substrate proteins such as RIPK1/RIP1 and RIPK2: this acts as a scaffold to organize a large signaling complex to promote autophosphorylation of MAP3K7/TAK1, and subsequent activation of I-kappa-B-kinase (IKK) core complex by MAP3K7/TAK1. Also recognizes and binds Lys-63'-linked polyubiquitin chains of heterotypic 'Lys-63'-/'Lys-48'-linked branched ubiquitin chains. Regulates the IL1-mediated translocation of NCOR1 out of the nucleus (By similarity). Involved in heart development.
Synonyms: TAB-2; KIAA0733; MAP3K7IP2; CHTD2
Tractability: Antibody: UniProt places it where antibodies can reach, with high confidence; its Gene Ontology location is reachable by antibodies, with high confidence. PROTAC: UniProt records ubiquitination sites on it; ubiquitination databases record sites on it; its protein half-life has been measured.
Safety:
Unwanted effects reported when the protein is acted on. In parentheses: how it was acted on, where the effect was seen, and who reports it.
diarrhea (source: ClinPGx)
Gene: Protein-coding gene on chromosome 6 (149,218,641 to 149,411,613, forward strand). Ensembl gene ENSG00000055208.
Subcellular location: Membrane; Endosome membrane; Lysosome membrane; Cytoplasm, cytosol
Pathways (Reactome):
Immune System: Alpha-protein kinase 1 signaling pathway; CLEC7A (Dectin-1) signaling; Downstream TCR signaling; FCERI mediated NF-kB activation; IRAK2 mediated activation of TAK1 complex; IRAK2 mediated activation of TAK1 complex upon TLR7/8 or 9 stimulation; Interleukin-1 signaling; JNK (c-Jun kinases) phosphorylation and activation mediated by activated human TAK1; NOD1/2 Signaling Pathway; TAK1-dependent IKK and NF-kappa-B activation; TICAM1,TRAF6-dependent induction of TAK1 complex; TRAF6-mediated induction of TAK1 complex within TLR4 complex; activated TAK1 mediates p38 MAPK activation
Signal Transduction: Nuclear signaling by ERBB4; TNFR1-induced NF-kappa-B signaling pathway
Disease: SARS-CoV-2 activates/modulates innate and adaptive immune responses
Gene Ontology:
Molecular function: K63-linked polyubiquitin modification-dependent protein binding; molecular adaptor activity; protein binding; zinc ion binding; ubiquitin binding
Biological process: canonical NF-kappaB signal transduction; defense response to bacterium; heart development; inflammatory response; non-canonical NF-kappaB signal transduction; positive regulation of canonical NF-kappaB signal transduction; positive regulation of protein kinase activity; regulation of MAPK cascade; response to lipopolysaccharide; negative regulation of autophagy; response to bacterium
Cellular component: cytoplasm; endosome membrane; lysosomal membrane; membrane; serine/threonine protein kinase complex; cytosol; nucleoplasm; plasma membrane
Genetic constraint (gnomAD): Loss-of-function variants: 3 observed, 66.18 expected, observed/expected ratio (o/e) 0.0453, 90% interval 0.02 to 0.12. The upper end of that interval is the gene's LOEUF score, 0.12, which puts it in group 1 of 6, group 1 being the genes least tolerant of losing a copy. Missense variants: 623 observed, 885.81 expected, observed/expected ratio (o/e) 0.7, 90% interval 0.66 to 0.75. Synonymous variants: 298 observed, 301.51 expected, observed/expected ratio (o/e) 0.99, 90% interval 0.9 to 1.09.
Homologues: Orthologues: chimpanzee TAB2 (99% identical), macaque TAB2 (99% identical), pig TAB2 (97% identical), dog TAB2 (97% identical), rabbit TAB2 (96% identical), mouse Tab2 (95% identical), rat Tab2 (94% identical), guinea pig TAB2 (91% identical), tropical clawed frog tab2 (78% identical), zebrafish tab2 (58% identical). Paralogues in human: TAB3 (40% identical), BTF3 (7% identical), BTF3L4 (7% identical).
Diseases named in the same sentence as TAB2 in open-access papers:
TAB2 is named in the same sentence as 66 diseases in open-access papers, as found by Europe PMC text mining. Sharing a sentence is not in itself a finding about the gene and the disease. The quoted sentences say what the papers report.
breast carcinoma (6 papers, 2012 to 2021). "SNP rs9485372, near the TGF-β activated kinase (TAB2) gene in chromosome 6q25.1, showed a consistent association with breast cancer risk across all four stages, with a P-value of 3.8×10−12 in the combined analysis of all samples." (PMID 22383897, 2012). "Single nucleotide polymorphism (SNP) rs9485372, near the TGF-beta activated kinase 1 (TAB2) gene at chromosome 6q25.1, was associated with breast cancer risk (P = 3.8×10−12)." (PMID 22383897, 2012). "TAB2 has been reported to contribute to steroid antagonist resistance in prostate and breast cancer." (PMID 34551195, 2021). "Because of its role in ER signaling, TAB2 is seen as a potential target for reversing tamoxifen resistance in breast cancer cells." (PMID 26036842, 2015). "We demonstrated previously that either Tab2 knock-down, or a peptide mimicking the Estrogen Receptor alpha domain interacting with Tab2, restore the antiproliferative response to Tamoxifen in Tamoxifen-resistant breast cancer cells." (PMID 27992601, 2016). "TAB2 and TAB3were reported to be able to form complex with TAK1, which induced breast cancer metastasis." (PMID 27009840, 2016). "Therefore, we asked whether the central domain of Tab2 was also able to interact with other receptors, specifically with AR that plays a role in the response/resistance of prostate cancer cells to anti-androgenic drugs, in analogy to anti-estrogens in breast cancer cells." (PMID 27992601, 2016). "A synthetic peptide mimicking this motif efficiently displaced Tab2 from interacting with recombinant Estrogen Receptor alpha in vitro, prompting us to test its efficacy using derivatives of the MCF7 breast carcinoma cell lines that are spontaneously resistant to Tamoxifen." (PMID 27992601, 2016). "Since TAB1 is not expressed and TAB2 in not O-GlcNAcylated in breast cancer by our previous results, the present study focus on whether TAB3 O-GlcNAcylationis participating in the metastasis of breast cancer." (PMID 27009840, 2016).
lung carcinoma (6 papers, 2020 to 2024). "It has been further reported that CLU inhibits lung cancer progression by inhibiting TGFBR1-induced TRAF6/TAB2/TAK1 complex recruitment and thus blocking the TAK1-NF-κB axis, indicating its tumor-suppressive function, which is consistent with our in vivo data." (PMID 35626071, 2022). "Results showed that upregulation of circ‐WHSC1 enhanced lung cancer progression by impairing the level of miR‐7 and increasing TAB2 expression." (PMID 34551195, 2021). "Inhibiting the circ-WHSC1/miR-7/TAB2 pathway might significantly attenuate lung cancer development, validating its oncogenic role in NSCLC and recommending it as a possible target for NSCLC treatment." (PMID 38505309, 2024). "We also investigated the relationship between circ‐WHSC1, miR‐7 and TAB2 in lung cancer tissues." (PMID 34551195, 2021). "Inhibition of the circ‐WHSC1/miR‐7/TAB2 pathway could effectively block the progression of lung cancer." (PMID 34551195, 2021). "Inhibition of the circ‐WHSC1/miR‐7/TAB2 pathway could effectively attenuate lung cancer progression." (PMID 34551195, 2021).
congenital heart defects (4 papers, 2019 to 2025). "Various studies have reported cases in which nonsense, or small insertion/deletion mutations of the TAB2 gene result in congenital heart disease and dilated cardiomyopathy." (PMID 39905300, 2025). "Haploinsufficiency of TAB2 caused by microdeletions of chromosome 6q25.1 in humans is associated with congenital heart defects (CHDs) and/or cardiomyopathy." (PMID 34990405, 2022). "Microdeletions encompassing TAB2 have been detected in various patients with congenital heart defects(CHD), indicating that haploinsufficiency of TAB2 causes CHD." (PMID 33974633, 2021). "Permanyer proposed that a variant in the TAB2 gene is associated with syndromic congenital heart disease, displaying congenital myxomatous degenerative heart valve disease, mild dysmorphic fascial anomalies and short stature in the surveyed family." (PMID 33974633, 2021). "Mutations in TGF-β–activated kinase 1 binding protein 2 (TAB2) have been implicated in the pathogenesis of dilated cardiomyopathy and/or congenital heart disease in humans, but the underlying mechanisms are currently unknown." (PMID 34990405, 2022). "And haploinsufficiency of TAB2 was blamed for a variety of congenital heart defects." (PMID 33974633, 2021). "However, some TAB2 mutations are associated only with dilated cardiomyopathy, without causing congenital heart disease." (PMID 39905300, 2025).
cardiac hypertrophy (3 papers, 2019 to 2025). "Tab2fl/fl-MCM mice also displayed cardiac hypertrophy and pulmonary congestion as assessed by heart weight to body weight and lung weight to body weight ratios, suggesting that TAB2 deficiency induced pathological cardiac remodeling and congestive heart failure." (PMID 34990405, 2022). "Previous research has demonstrated that reactive oxygen species generated during cardiac hypertrophy progression can induce the auto-ubiquitination of TRAF6, leading to the recruitment of TAB2 and the subsequent binding to TAK1, thereby activating the TAK1-mediated prohypertrophic signaling pathway." (PMID 40880411, 2025).
cardiomyopathy (3 papers, 2018 to 2025). A disease of the heart muscle or myocardium proper. "Haploinsufficiency of TAB2 is known to cause congenital heart defects and cardiomyopathy due to its important roles in cardiovascular tissue, both during development and through adult life." (PMID 29700987, 2018). "Genetic inactivation of RIPK1 rescues TAB2 deficiency–induced cardiomyopathy in vivo." (PMID 34990405, 2022). "Subsequently, we induced their differentiation into cardiomyocytes to establish an in vitro TAB2-knockout cardiomyopathy model." (PMID 39905300, 2025). "While it is true that not all individuals with deficiencies in TAB2 will experience congenital heart defects, many will experience cardiomyopathy or heart disease at some point in their lives." (PMID 29700987, 2018).
cervical cancer (3 papers, 2021 to 2025). A primary or metastatic malignant neoplasm involving the cervix. "For example, CXCL8, CLEC9A, and TAB2 have been identified as crucial mRNA biomarkers related to immune microenvironment alterations in cervical cancer." (PMID 40003691, 2025). "According to our findings, upregulated TAB2 was correlated to stem cell-like properties of cervical cancer." (PMID 34306095, 2021). "The cell function experiments demonstrated that knockdown of TAB2 reduced the stemness of cervical cancer cells and, importantly, prevented cervical cancer progression." (PMID 34306095, 2021). "Collectively, the therapeutic scheme targeting TAB2 may provide an option for overcoming tumor relapse and chemoresistance of cervical cancer via obstructing stemness maintenance." (PMID 34306095, 2021). "Immunohistochemistry staining of TAB2 in normal and cervical cancer tissues was performed." (PMID 34306095, 2021).
dilated cardiomyopathy (3 papers, 2021 to 2025). Cardiomyopathy which is characterized by dilation and contractile dysfunction of the left and right ventricles. "TAB2 frameshift mutations have been linked to dilated cardiomyopathy (DCM), while the exact mechanism needs further investigation." (PMID 39905300, 2025). "Here, we identified a key disease mechanism for TAB2 deficiency–induced dilated cardiomyopathy, which involves aberrant RIPK1 activation and the induction of RIPK1-dependent apoptosis and necroptosis." (PMID 34990405, 2022). "Taken together, these data reveal a key role for RIPK1-dependent apoptosis and necroptosis in the pathogenesis of TAB2 deficiency–induced dilated cardiomyopathy." (PMID 34990405, 2022). "We showed that acute deletion of TAB2 in the adult heart led to dilated cardiomyopathy through the induction of apoptotic and necroptotic cell death, recapitulating the cardiac phenotype in patients with TAB2 mutations." (PMID 34990405, 2022). "TAB2 polymorphisms were associated with dilated cardiomyopathy susceptibility and prognosis in the Chinese population." (PMID 33974633, 2021). "To gain insight into the molecular mechanism via which TAB2 wiped out the phenotype associated with dilated cardiomyopathy in cardiomyocytes, we employed RNA-Seq techniques to detect and analyze variations in gene expression profiles between groups of WT and KO cardiomyocytes." (PMID 39905300, 2025). "Loss of TAB2 in the adult heart induces dilated cardiomyopathy and heart failure." (PMID 34990405, 2022). "Our results also suggest that targeting RIPK1-mediated cell death signaling may represent a promising therapeutic strategy for TAB2 deficiency–induced dilated cardiomyopathy." (PMID 34990405, 2022). "Therefore, acute deletion of Tab2 in the adult heart induced cardiac remodeling and heart failure, recapitulating the phenotype of dilated cardiomyopathy in humans with TAB2 gene mutations." (PMID 34990405, 2022). "By generating cardiomyocyte-specific Tab2-KO mouse models, we showed that genetic ablation of TAB2 in the adult heart promoted apoptotic and necroptotic cell death, leading to dilated cardiomyopathy and heart failure." (PMID 34990405, 2022). "Cardiomyocyte-specific deletion of Tab2 in mice triggered dilated cardiomyopathy with massive apoptotic and necroptotic cell death." (PMID 34990405, 2022). "In summary, TAB2 abatement cardiomyocytes mimic dilated cardiomyopathy in vitro." (PMID 39905300, 2025). "However, it was confirmed once again that calcium ion homeostasis imbalance was not the priming cause of the development of dilated cardiomyopathy (DCM) resulting from TAB2 deficiency." (PMID 39905300, 2025). "Following the findings by Eschenhagen and Carrier (2019), which identified myotome disturbance as a prevalent phenotype of Dilated Cardiomyopathy (DCM), our study focuses on the structural alterations in TAB2-knockout cardiomyocytes." (PMID 39905300, 2025). "Our Tab2-KO mice developed dilated cardiomyopathy but not CHDs." (PMID 34990405, 2022). "However, in the acute TAB2 deletion model, the compensatory effect did not occur when the gene is acutely deleted in the adult heart, leading to early-onset dilated cardiomyopathy." (PMID 34990405, 2022).
hepatocellular carcinoma (3 papers, 2014 to 2019). A malignant tumor that arises from hepatocytes. "Thus, we anticipate that inhibition of TAB2 might selectively kill stressed hepatocytes such as hepatocellular carcinoma cells." (PMID 24498425, 2014). "On the contrary, IL-17A inhibited autophagy via TAB2/TAB3-p38 mitogen-activated protein kinase pathways and mTOR signaling in Hepatocellular carcinoma (HCC) cells and keratinocytes." (PMID 31921197, 2019).
non-small cell lung carcinoma (3 papers, 2021 to 2024). A group of at least three distinct histological types of lung cancer, including non-small cell squamous cell carcinoma, adenocarcinoma, and large cell carcinoma. "The extended expression of TAK1, which can trigger the TAB2 molecule, is linked to non-small cell lung cancer." (PMID 39768951, 2024). "Prolonged activation of TAK1, which the TAB2 protein can induce, is associated with non-small-cell lung cancer." (PMID 39061149, 2024).
prostate carcinoma (3 papers, 2016 to 2025). A carcinoma that arises from epithelial cells of the prostate gland. "Tab2 interacts also with steroid receptors and dismisses NCoR from antagonist-bound Estrogen and Androgen Receptors on gene regulatory regions, thus modifying their transcriptional activity and leading to pharmacological resistance in breast and prostate cancer cells." (PMID 27992601, 2016).
squamous cell carcinoma (3 papers, 2022 to 2024). A carcinoma arising from squamous epithelial cells. "A study by Liu and colleagues found that increased expression of TAB2 promotes the development of squamous cell carcinoma of the oral cavity by stimulating the proliferation of tumor cells, which is associated with a poor prognosis." (PMID 39061149, 2024).
atherosclerosis (2 papers, 2019 to 2021). A disease characterized by the build-up of fatty material and calcium deposition in the arterial wall resulting in partial or complete occlusion of the arterial lumen. "MiR-181a-5p and miR-181a-3p mimetics retard atherosclerosis progression through targeting TAB2 and NEMO, respectively, to block NF-κB activation and vascular inflammation." (PMID 31064980, 2019). "MiR-181a-5p and miR-181a-3p mimetics retard atherosclerosis progression through blocking NF-κB activation and vascular inflammation by targeting TAB2 and NEMO, respectively." (PMID 31064980, 2019).
autoimmune disease (2 papers, 2016 to 2021). A disorder resulting from loss of function or tissue destruction of an organ or multiple organs, arising from humoral or cellular immune responses of the individual to their own tissue constituents. "Notably, the interaction between TRIM38 and TAB2/3 is weakened in RA, resulting in an excess expression of TAB2/3 and proinflammatory cytokines, indicating the essential roles of TRIM38 in modulating autoimmune disease severity." (PMID 34177938, 2021).
E. coli infection (2 papers, 2020 to 2021). "On the one hand, down-expressed dMyc could down-regulate miR-277 expression to ensure the elevated expression of imd and Tab2 at the early stage of E. coli infection to promote the expression of Dpt against pathogenic bacteria." (PMID 32810129, 2020). "The E. coli infection-induced downregulation of TAB2 was restored by inhibiting miR-155, demonstrating that miR-155 can regulate TAB2 during E. coli infection." (PMID 33985523, 2021). "As expected, the transfection of TAB2 siRNA resulted in decreased phosphorylation of NF-κB p65 upon E. coli infection compared with that with the transfection of siRNA control." (PMID 33985523, 2021). "As expected, the expression levels of Dpt in both imd-RNAi and Tab2-RNAi mutant flies are significantly lower than the control upon E. coli infection." (PMID 32810129, 2020). "To test this point, we further monitored the dynamic expressions of Dpt, dMyc, miR-277, imd and Tab2 in this wild-type flies at 0, 3, 6, 12, 24 and 48 h after E. coli infection." (PMID 32810129, 2020). "Moreover, we measured the protein level of TAB2 in U251 cells transfected with anti-miR-155 after E. coli infection." (PMID 33985523, 2021). "In addition, the mRNA and protein expression of TAB2 were significantly downregulated in U251 cells upon E. coli infection, which was the opposite trend compared with that of miR-155." (PMID 33985523, 2021).
Epithelial Ovarian Cancer (2 papers, 2019 to 2021). "TAB2 gene exhibits polymorphism and is associated with ovarian cancer susceptibility." (PMID 33521362, 2021).
head and neck squamous cell carcinoma (2 papers, 2024 to 2025). A squamous cell carcinoma that arises from any of the following anatomic sites: lip and oral cavity, nasal cavity, paranasal sinuses, pharynx, larynx, and salivary glands. "TAB2 is associated with squamous cell carcinoma of the head and neck." (PMID 39061149, 2024).